STAT3 (signal transducer and activator of transcription 3)
Diseases named in the same sentence as STAT3 in open-access papers (continued):
Sharing a sentence is not in itself a finding about the gene and the disease.
leukemia (continued). "STAT3 gain-of-function mutations are found in a significant proportion of natural killer cell leukemias and may serve in the future as a therapeutic target for these leukemias." (PMID 30116531, 2018). "In leukaemia U937 cell lines and myelogenous cell lines (U266 and U937), genipin inhibited the constitutive STAT3 activation and downregulated the expression of STAT3 target genes including Bcl-2, Bcl-xL, survivin, cyclin D1, and VEGF." (PMID 40003568, 2025). "For these reasons, targeting STAT3 with small molecule inhibitors has become an attractive therapeutic strategy for leukemia treatment, showing promising results in preclinical studies." (PMID 40943567, 2025). "The STAT family, particularly STAT3, regulates gene expression upon JAK activation and is associated with the development of several cancers, including leukemia." (PMID 40362240, 2025). "Another study showed that wogonin reversed resistance by inhibiting Nrf2 signaling via inactivating the STAT3/NF‐κB pathway in human leukemia cells." (PMID 41164269, 2025). "JAK2 mutations can activate STAT3 and STAT5, transcription factors that promote the expression of immune checkpoint molecules, such as PD-L1, on leukemia cells." (PMID 40486651, 2025). "There are already clinical studies aiming to inhibit APE1 in pancreatic, prostate, bladder, ovary, and other types of cancer (NCT0337508), and STAT3 (NCT00955812) in leukemia." (PMID 41090323, 2025). "In AML, STAT3 from the nuclear extract of patient leukemia cells stimulated with IL-6 binds the probe of an IL-6 responsive element derived from the ICAM1 promoter." (PMID 39034990, 2024). "Reviews have highlighted that the CXCL12/CXCR4/ACKR3 axis can activate the STAT3 pathway, leading to leukemia development." (PMID 38920657, 2024). "Data on the frequencies of STAT3 and STAT5B gene mutations in γδT-LGL leukemia are rare and inconsistent." (PMID 39161592, 2024). "In leukemias, the visible overactivation of STAT3 accelerates leukemia cell proliferation, blocks leukemia cell differentiation, and inhibits apoptosis of leukemia cells." (PMID 38999955, 2024). "Accordingly, phosphorylation of STAT3 in response to G-CSF in murine leukemia cells only occurred if both isoforms were present." (PMID 38806478, 2024). "Recent studies showed that leukemia stem cells (LSCs) play essential roles in the pathogenesis of leukemia by targeting several signaling pathways, including Notch, Wnt, Hedgehog, and STAT3." (PMID 37692500, 2024). "Three days of G-CSF stimulation resulted in a significant increase of STAT3 Y705 phosphorylation only in WT leukemia cells." (PMID 38806478, 2024). "Here, we report clinical findings, immunophenotypic data, TCR-γ, -β, and -δ gene rearrangements, and STAT3 and STAT5B mutation frequencies for a series of 15 patients with γδT-LGL leukemia associated with rheumatologic diseases." (PMID 39161592, 2024). "Inhibition of abnormal activation of STAT3 has been proven to be effective in the treatment of leukemia." (PMID 38611876, 2024). "Previous studies have already shown that LicA significantly inhibits the phosphorylation and nuclear localization of STAT3 in leukemia cells." (PMID 37238935, 2023). "In vitro studies based on the K562 leukemia cell line showed the influence of STAT3 silencing on several cellular processes." (PMID 38067351, 2023). "To confirm the role of the JAK-STAT3 pathway, we treated leukemia cell lines with sorafenib and Stattic, a STAT3 inhibitor, and detected the BCL2 expression using Western blot." (PMID 37887047, 2023).
leukemia (continued). "Although myeloid cells constitutively express STAT3 both in normal settings and leukemia, we noticed a smaller number of myeloid cells expressing p-STAT3 in leukemia." (PMID 37835401, 2023). "The persistency of leukemia in vivo in Vav3-/- chimeras suggests that Vav3-/- BCR-ABL1 leukemia has evolved mechanisms of escape relying on RAC-independent pathways such as STAT3 signaling pathways." (PMID 34711926, 2022). "SI-109, a peptide stemmed from the STAT3-binding motif of the protein gp130, was utilized to develop a peptide-based PROTAC termed as SD-36, which achieved potent STAT3 degradation and inhibited leukemia and lymphoma in vitro and in vivo." (PMID 35410300, 2022). "CaMKIIγ is also highly activated in leukemia stem/progenitor cells and promotes cell survival and self-renewal by activating β-catenin, NF-κB, and STAT3 signaling." (PMID 35267623, 2022). "CaMKIIγ is also overactivated in leukemia stem cells and upregulates Wnt/β-catenin, NF-κB, and STAT3 signaling, thereby promoting cell survival and self-renewal." (PMID 36432068, 2022). "IL-10 mediated STAT3 activation as well as somatic STAT3 GOF mutations increase expression of MYC and thereby drive metabolic activation of ANKL cells, fueling leukemia cell survival and proliferation." (PMID 35865518, 2022). "It was shown to activate both STAT5 and STAT3 and improve antitumor efficacy in leukemia (NALM6) mouse models." (PMID 35270020, 2022). "It has also been shown to play a role in the regulation of the Wnt, STAT3 and RAS/MAPK pathways, which have been implicated in leukemia development." (PMID 35408829, 2022). "The STAT3–MYC axis promotes the survival of leukemia stem cells by regulating SLC1A5 and oxidative phosphorylation." (PMID 36275721, 2022). "Constitutive expression of STAT3 molecules has been confirmed in a variety of leukemias including CLL and B cell lymphomas." (PMID 35897737, 2022). "It seems that IBS and MBS, by decreasing STAT3 phosphorylation, trigger apoptosis, inhibit cell proliferation, and attenuate leukemia cell stemness." (PMID 33807148, 2021). "Polyphenols including quercetin and curcumin have also been shown to act indirectly on inhibition of STAT3 in a number of leukaemia cell lines (HL-60, U-937 and K562)." (PMID 33802972, 2021). "The anti-leukemia activity of leonurine was illustrated by regulating miR-18a-5p/SOCS5/JAK2/STAT3 axis." (PMID 33935775, 2021). "In leukemia cells, abnormal expression and activation of STAT3 always occur, which accelerate proliferation, block differentiation, and inhibit apoptosis by inducing anti-apoptotic gene expression." (PMID 33796529, 2021). "For example, STAT3 has been reported to be involved in the regulation of gene expression level with JAK/STAT signalling pathway in childhood leukemias." (PMID 34316412, 2021). "In leukemia cells, the inhibition of the STAT3 pathway can promote the intracellular accumulation of Adriamycin and down‐regulate the expression levels of MDR1 and MRP1, thus increasing drug sensitivity." (PMID 34129726, 2021). "STAT3 promotes the proliferation of leukemia cells through AKT/STAT3, Ras/Raf/MAPK and PI3K/AKT/mTOR, and other pathways." (PMID 33796529, 2021). "In leukemia cells, STAT3 was mainly concentrated in the centrosome region where microtubules were more stable and hyperacetylated." (PMID 34526901, 2021). "For our study, we concluded leonurine exerted its anti-leukemia effect at least partially by suppressing JAK2/STAT3 signaling pathway." (PMID 33935775, 2021). "STAT3 has shown a direct link to the development of leukaemia, by promoting the proliferation of leukaemia cells, regulating the differentiation and blocking the apoptosis of leukaemia cells." (PMID 33802972, 2021). "Taken together, leonurine exerts significant anti-leukemia efficacy in CML by regulating miR-18a-5p/SOCS5/JAK2/STAT3 axis." (PMID 33935775, 2021).
leukemia (continued). "STAT3 inhibitors are being evaluated as chemotherapeutic agents in leukemias, due to their strong pro-apoptotic activity." (PMID 32150944, 2020). "For instance, KITD816V, which is frequently found in core-binding factor (CBF)-AML leukemias, stimulates autophagy through activation of STAT3." (PMID 31963765, 2020). "Specifically, recurrent Signal transducer and activator of transcription 3 (STAT3) mutations in the Src‐homology 2 (SH2) domain have been reported in approximately 40% of both T‐ and NK‐LGL leukemia patients, with Y640F and D661Y the most commonly reported." (PMID 32710512, 2020). "Another study showed that dasatinib suppresses the phosphorylation of STAT3/STAT5 in leukemia-initiating cells." (PMID 31655606, 2019). "Preclinical studies with OPB-31121 have shown that the compound inhibits STAT3 DNA binding and enhances the activities of chemotherapy drugs in leukemia and gastric cancer models." (PMID 31671769, 2019). "STAT1 and STAT3 activation is important for the terminal differentiation of immature leukemia cells." (PMID 31117333, 2019). "Accordingly, the inhibition of STAT3 activity through specific inhibitors induced cell death in the pre-leukaemia cell, and shRNA directed against Stat3 led to a longer latency in pre-B ALL development." (PMID 28819864, 2018). "Kortylewski’s group has pioneered ODN decoy-based STAT3 inhibition in both leukemias and B-cell lymphomas." (PMID 30340426, 2018). "As an important factor downstream of the JAK-STAT signal transduction pathway, STAT3 is involved in the pathogenesis of autoimmune diseases, myeloproliferative neoplasms, solid tumor, leukaemia, and many other diseases." (PMID 30622613, 2018). "The E/R fusion gene can also induce signal transducer and activator of transcription 3 (STAT3) activation, aiding to the self-renewal and leukemogenic activity of leukemia cells." (PMID 28418909, 2017). "In concordance, ruxolitinib treatment of heterozygous mutant STAT3-harboring NK cell lymphoma/leukemia cell lines reduced STAT3 phosphorylation to a smaller extent compared to WT cells." (PMID 29228628, 2017). "A previous study has reported that inhibition of mTOR prevents the migration and invasion of leukemia cells through the inhibition of STAT3 phosphorylation." (PMID 29212252, 2017). "STAT3 mutations have been described in 30-40% of T-large granular lymphocyte (T-LGL) leukemia patients, leading to STAT3 pathway activation." (PMID 28977911, 2017). "Growing evidence has revealed that loss of SHP-1 leads to constitutive activation of STAT3 in hematologic malignancies, since ectopic expression of SHP-1 in leukemia cells substantially decreases the levels of activated STAT3." (PMID 28594363, 2017). "A recent study demonstrated that transcription factor STAT3 was involved in the regulation of ABCB1 transcription by binding with its promoter region in leukemia cells." (PMID 27409663, 2016). "Both the PI3K/Akt and Jak2/Stat3 signaling have been shown to play pivotal roles in tumor cell proliferation, survival, invasion and immunosuppression in many tumors including leukemia." (PMID 27176825, 2016). "At least one of the SYK probesets was positively correlated with 33 out of the 38 probesets suggesting a high degree of co-regulation of SYK, SYK dependent STAT3 targets and anti-apoptotic genes in leukemia samples." (PMID 26285772, 2015). "Nonetheless, five different leukemia cell lines treated with cucurbitacin B showed cell growth inhibition, which was achieved by suppression of both STAT3 activation and RAF/ERK kinase pathways." (PMID 25674792, 2015). "The most distal motifs of the LIFr C-terminus can induce myeloid differentiation of leukemia cells by enhancing STAT3 phosphorylation." (PMID 26329521, 2015). "WT-1 regulates the oncogenicity of leukemia cells by activating JAK/STAT3 and MAPK signaling, therefore we explored the role of JAK/STAT3 and MAPK signaling in the WT1-mediated resistance to DOX." (PMID 26462627, 2015).
leukemia (continued). "For example, pyrimethamine, an antimalarial drug, inhibits STAT3 phosphorylation and is in clinical investigation for treatment of leukemia." (PMID 24662938, 2014). "The tumor promoting role of STAT3 in leukemia formation has been confirmed in mice: transduction of bone marrow (BM) with constitutively active versions of STAT3 rapidly induced leukemia in mice." (PMID 24473086, 2014). "Similar results were obtained in HEL leukemia cells that harbor a JAK2-V617F mutation and the resulting hyper-phosphorylated STAT3 on Tyr-705." (PMID 24930769, 2014). "The addition of IFN-γ to leukemia blasts also translated into the up-regulation of phosphorylated STAT3, a phenomenon that was paralleled by the increase of IDO1 protein expression." (PMID 24903009, 2014). "In summary, for the first time we report the mechanism of TBr mediated cell death in human leukemia cell lines by targeting STAT3 and ERK pathways." (PMID 25383546, 2014). "Arsenic trioxide, an inorganic compound used to treat leukemia, inhibits STAT3 phosphorylation possibly by inhibiting its upstream kinases." (PMID 24662938, 2014). "Here, we report the characterization of STAT3 protein regulation by STAT3-interacting protein (STATIP1) in the leukemia cell line K562, which demonstrates constitutive BCR-ABL TK activity." (PMID 25417721, 2014). "Of the seven STAT family members (STAT1-STAT6, with two independent genes encoded STAT5A and STAT5B), STAT3, as well as STAT5 to some extent, are most frequently activated in quite a lot human solid tumors and leukemias." (PMID 23704931, 2013). "It has been recently reported that STAT3 inhibition reversed drug resistance of leukemia cells by down-regulating MDR1." (PMID 23704931, 2013). "Similar to existing data concerning solid tumors, our data suggests that FoxM1 and STAT3 mRNA levels are concomitantly overexpressed in leukemia-resistant K562-R cells." (PMID 23110199, 2012). "In summary, it was demonstrated that the activation of STAT3 was higher in drug resistant K562/A02 leukemia cells, and also in MCF-7/ADR cells." (PMID 21677772, 2011). "p38 and STAT3 are involved in apoptosis induced by trophic factor withdrawal in human leukemia cell line and pancreatic beta-cell line, respectively." (PMID 21264226, 2011). "It is reported that the proliferation and apoptotic resistance of leukemia cells was closely related to several oncogenic signaling pathways such as Akt/mTOR, Stat3 and ERK." (PMID 19897545, 2011). "Icaritin both reduced Jak-2, p-Stat3 and p-Akt expression at a dose- and time-dependent manner, suggesting that Icaritin also disturbs Jak2/Stat3/Akt signal pathway and facilitates the growth-arrest of leukemia cells." (PMID 21887305, 2011). "Furthermore, our results align with a growing body of literature indicating that oncogenic STAT3 activation contributes to immune evasion, chemoresistance, and disease persistence in leukemia." (PMID 40943567, 2025). "While all cells remained CD11b+, solely leukemia cells expressing both STAT3 isoforms responded to G-CSF by notable upregulation of the granulocytic surface marker Gr-1, while on the mRNA level expression of the G-CSF receptor (Csf3r) was comparable in suspension culture." (PMID 38806478, 2024). "Structural activation of STAT3 has been shown in many forms of leukemia, including erythroleukemia." (PMID 38611876, 2024). "EZH2 activates STAT3 signaling via STAT3 methylation in leukemia cells." (PMID 39730061, 2024). "STAT3 deficiency (STAT3–/–) in donor T cells prevents graft-versus-host disease (GVHD), but the impact on graft-versus-leukemia (GVL) activity and mechanisms of GVHD prevention remains unclear." (PMID 37526084, 2023). "The p-STAT3 expression was significantly upregulated after sorafenib treatment using Western blot, suggesting that the JAK-STAT3 pathway might be involved in the resistance of leukemia cells to sorafenib." (PMID 37887047, 2023).
leukemia (continued). "Further work in this area is warranted because compounds can have many clinical applications in addition to cancer therapy: Effects of STAT3 ablation in natural killer (NK) cells suggested that STAT3 inhibitors can be used to stimulate cytolytic activity of NK cells against leukemia." (PMID 37182134, 2023). "Pyrimethamine showed on-target activity, as assessed by inhibition of expression of STAT3-dependent genes, in a clinical trial of chronic lymphocytic leukemia, a disease in which the leukemia cells are nearly always driven by increased STAT3 transcriptional activity." (PMID 34953855, 2022). "Similarly, the current RT-qPCR results showed that downregulated STAT3 and c-Myc in treated HL60 leukemia cells with TQ was associated with a significant increase in cell apoptosis (p < 0.001)." (PMID 35337104, 2022). "RNAi-mediated STAT3 silencing accelerated the sensitization of leukemia cells to nilotinib treatment, and STAT3-dependent energy metabolism regulation could be another underlying mechanism for regaining nilotinib response." (PMID 36033954, 2022). "The STAT3 mutation frequency was not different in the cohorts of T-LGL leukemia with and without SS, totaling 57% (12 of 21 patients) in the cohort of patients with SS and 60% (27 of 45 patients) in the cohort with RD but without SS (p = 1)." (PMID 36362126, 2022). "Arsenic trioxide, which has been reported as a potential therapeutic agent for RA, was predicted to target MAPK1; it has also been approved to treat leukemia and reported to regulate the Treg and Th17 cell balance by modulating STAT3 expression in treatment-naïve RA patients." (PMID 35140805, 2022). "STAT3 is generally believed to act centrally in the survival of TCRαβ CD8 T-LGL leukemia cells." (PMID 34873301, 2022). "In addition, FLT3 inhibitors have been shown to cause anti-proliferative activity, in leukaemia cell lines with FLT3-ITD, through the downregulation of MCL-1 and BIRC5, the latter via the STAT3/5 pathway." (PMID 34638823, 2021). "Our results indicated that SOCS5/JAK2/STAT3 was involved in anti-leukemia process of leonurine and that SOCS5 may be a potential diagnostic marker and therapeutic target for CML." (PMID 33935775, 2021). "NF-κB and STAT3 and their interactions are promising targets for leukaemia treatment." (PMID 33802972, 2021). "After coculture VEC-T cell or OE-IL-10-T cell with leukemia cells for 3 h, compared with VEC-T group, the leukemia cells treated with OE-IL-10-T cells induced a slight increase in the phosphorylation of STAT3 and AKT, and a mild decrease in the phosphorylation of ERK." (PMID 34392305, 2021). "Activated nuclear STAT3 has been detected in multiple forms of leukaemia." (PMID 33802972, 2021). "Since MIR-574/3P gene is known to suppress proliferation and induces apoptosis of chronic myeloid leukemia (CML) cells via targeting IL6/JAK/STAT3 pathway, the findings of this study provide novel insights into the association of ADAM6 with miR-574-3p signaling pathway in leukemia." (PMID 34249950, 2021). "STAT3 downregulation of Casp8 has also been shown in the human leukemia HL-60 cell line." (PMID 33557010, 2021). "Abnormal STAT3 activation is often detected in many human cancer cells, including leukemia." (PMID 31117333, 2019). "Similarly, the STAT3 decoy heightens the response of head and neck cancer cells to bortezomib, ovarian cancer cells to paclitaxel, and leukemia cells to Adriamycin." (PMID 31671769, 2019). "Both NF-κB and STAT3 are proven to be downstream targets of ABL1 in leukemia." (PMID 31396300, 2019). "Targeting STAT3 can provide highly specific approach to treat failed EG responses in leukemia." (PMID 29593731, 2018). "The inhibitory effect of cucurbitacin B on STAT3 was examined in the leukemia cell line K562." (PMID 30217007, 2018).